BGN (biglycan)
Diseases named in the same sentence as BGN in open-access papers (continued):
Sharing a sentence is not in itself a finding about the gene and the disease.
metastatic cancer (1 paper, 2022). A carcinoma which has spread from the original site of growth to another anatomic site. "There are five genes (BGN, THBS2, SPARC, CDH11 and SPP1) in metastatic cancer tissues that are significantly higher than non‐metastatic cancer tissue at the transcriptomics level, while only BGN and THBS2 were significant difference in protein expression between metastatic and non‐metastatic cases." (PMID 36377223, 2022).
neuroblastoma (1 paper, 2024). Neuroblastoma (NB) is the most common solid, extracranial childhood tumor. "For example, nuclear factor kappa B-induced upregulation of BGN was found to reduce the nitric oxide-induced apoptosis of human neuroblastoma cells, while DCN has been demonstrated to exert protection against hydrogen peroxide-induced apoptosis of retinal pigment epithelial cells." (PMID 38786104, 2024).
nonalcoholic steatohepatitis (1 paper, 2024). "Patients with nonalcoholic steatohepatitis (NASH) had higher circulating levels of serum biglycan levels than controls which correlated with fibrosis score." (PMID 39600538, 2024).
oral squamous cell carcinoma (1 paper, 2023). "Low DCN expression levels, along with increased biglycan expression, has been shown to correlate with a poorer outcome for oral squamous cell carcinoma patients." (PMID 37760543, 2023).
pancreatic ductal adenocarcinoma (1 paper, 2022). An infiltrating adenocarcinoma that arises from the epithelial cells of the pancreas. "In addition, BGN was found to drive EMT in pancreatic ductal adenocarcinoma." (PMID 36589754, 2022).
papillary thyroid carcinoma (1 paper, 2026). "This study aimed to investigate the endocrine and paracrine roles of BGN in papillary thyroid carcinoma (PTC) to elucidate the underlying molecular mechanisms driving PTC development." (PMID 41328346, 2026). "Despite these observations, the transcriptional regulatory mechanisms underlying BGN expression in papillary thyroid carcinoma (PTC) and its functional significance within the tumor microenvironment (TME) remain poorly understood." (PMID 41328346, 2026).
polycythemia (1 paper, 2021). Abnormally high mass or concentration of red blood cells in the blood, either due to an increase in erythropoiesis or a decrease in plasma volume. "Alternatively, angiogenesis in cancer could be affected by biglycan through the stabilization HIF-2α, which is induced by TLR2 interaction with biglycan and results in the induction of erythropoietin (Epo) synthesis and polycythemia." (PMID 34917515, 2021).
proliferative diabetic retinopathy (1 paper, 2022). Advanced retinopathy due to diabetes mellitus characterized by the formation of new vessels in the retina. "We analyzed the expression of ADAMTS proteinases ADAMTS-1, -2, -4, -5 and -13; their activating enzyme MMP-15; and the degradation products of proteoglycan substrates versican and biglycan in an ocular microenvironment of proliferative diabetic retinopathy (PDR) patients." (PMID 36144730, 2022).
psoriasis (1 paper, 2025). An autoimmune condition characterized by red, well-delineated plaques with silvery scales that are usually on the extensor surfaces and scalp. "Regarding BGN, KLF2, and LEPR, the staining properties of epidermal cell nuclei, as well as dermal infiltrating cells and vascular endothelial cells tended to be decreased in both nonlesioned and lesioned areas of patients with AD versus normal and clinical controls (psoriasis)." (PMID 39938773, 2025).
skin aging (1 paper, 2021). The gradual irreversible changes in structure of skin that occur as a result of the passage of time.. "As biglycan and decorin play a role in the integrity of collagen fibers, their degradation may lead to collagen fiber decomposition, as well as skin aging." (PMID 33573338, 2021).
thrombosis (1 paper, 2021). "In this study, we have shown that genetic deletion of the small proteoglycan biglycan interferes with hemostasis and protects against arterial thrombosis induced by reduced platelet binding to the injured vessel." (PMID 34830059, 2021).
Tinnitus (1 paper, 2023). Tinnitus is an auditory perception that can be described as the experience of sound, in the ear or in the head, in the absence of external acoustic stimulation. "In conclusion, measurement of ASR inhibition by BGN appears to be a simple non-invasive method of predicting the development of noise-induced tinnitus in laboratory rodents." (PMID 38144362, 2023).
urachal adenocarcinomas (1 paper, 2018).
urothelial bladder cancer (1 paper, 2013). "Therefore, aim of the present study was to assess the possible implication of the small leucine-rich proteoglycan biglycan in progression of human urothelial bladder cancer." (PMID 24223213, 2013).
tumor (156 papers, 2006 to 2026). "Tumor growth curves and tumor weight measurements showed that NR2F2 overexpression significantly promoted tumor growth, while BGN knockdown partially inhibited the tumor growth promotion caused by NR2F2 overexpression." (PMID 41328346, 2026). "Elevated biglycan expression has been linked to poor outcomes in hypoxic tumours and to the reactivation of dormant BC cells via metabolic reprogramming, supporting its role as a driver of metastatic recurrence." (PMID 41463344, 2025). "For tumour cells, the expression of biglycan by BC stem cells was associated with a more aggressive migration and invasion of these cells, whereas the loss of biglycan led to a reduced metabolism and a decreased tumourigenic phenotype." (PMID 41463344, 2025). "Biglycan-deficient breast cancer stem cells showed reduced metabolism and decreased ability to form tumor spheroids." (PMID 39334952, 2024). "(2020) reported that BGN expression is significantly higher in GC tissues and is associated with lymph node metastasis, and depth of tumor invasion." (PMID 37361568, 2023). "Elevated BGN was associated with shorter overall survival as well as unfavorable clinicopathological features, including tumor size, serosa invasion and length of hospitalization." (PMID 35096572, 2021). "Recently we identified biglycan (BGN) as a tumor endothelial cell (TEC) marker that is associated with tumor progression in various cancers." (PMID 33709550, 2021). "The small leucine-rich proteoglycan biglycan has been described to be up-regulated in several cancer types and to be associated with tumor progression and worse prognosis of patients." (PMID 33809543, 2021). "In some cancers, BGN up‐regulation in whole‐tumor tissues has been linked to advanced cancer progression or poor patient prognosis." (PMID 33709550, 2021). "High BGN expression in a tumor was significantly associated with histology and T factor (p < 0.0001, p = 0.0135)." (PMID 33709550, 2021). "These diverse implications of biglycan in triggering and modulating inflammation and the immune response suggest an important role for this proteoglycan in the development of tumor-associated inflammation." (PMID 34917515, 2021). "Changes in HIF-2α expression levels have been described in a variety of solid tumors and are linked to TAMs and HIF-2α is, similar to biglycan, associated with late tumor progression stages." (PMID 34917515, 2021). "We observed that biglycan-deficient tumor vessels showed normalized vasculature phenotypes, such as increased pericyte coverage and decreased vessel perfusion, leading to a less hypoxic environment and increased drug delivery." (PMID 33966638, 2021). "Ongoing research indicates that the dysregulation of BGN is associated with tumor cell invasion and migration." (PMID 28687755, 2017). "In accordance, in an in vivo xenograft tumor model knock-down of BGN in tumor cells prior to xenografting caused acceleration of tumor growth and tumor cell proliferation." (PMID 24223213, 2013). "Collectively, the experimental data suggest that high biglycan expression is associated with reduced tumor cell proliferation." (PMID 24223213, 2013). "Furthermore, BGN knockdown partially reduced the tumor growth promotion caused by Nr2f2 overexpression." (PMID 41328346, 2026). "Previous reports have implicated CAF-derived BGN in tumor progression across several cancer types." (PMID 41465449, 2025). "Notably, BGN, a proteoglycan, has been associated with tumor EC signatures, further supporting the anti-inflammatory role of M2-like macrophages observed in the infected dataset." (PMID 38767331, 2024). "Meanwhile, another class I member biglycan secreted by the cancer-associated fibroblasts (CAFs) is demonstrated to cause a poor prognosis and be associated with the immunosuppressive TME, and high biglycan expression is also found to be associated with tumor invasiveness in several types of cancer." (PMID 37504302, 2023).
tumor (continued). "Thus, future investigations on the role of biglycan in modulating autophagy in tumour-associated macrophages and its effects on tumour angiogenesis would provide invaluable information on matrix-derived autophagic stimuli in cancer inflammatory response." (PMID 34982945, 2022). "Hence, in vitro and in vivo experiments will be needed to further elucidate the precise underlying molecular mechanisms of BGN in the tumor immune response." (PMID 35096572, 2021). "Importantly, an emerging body of evidence points to the vital implications of the SLRPs decorin and biglycan in several hallmarks of cancer and regulating tumor-associated pathways, such apoptosis, proliferation, angiogenesis, inflammation, and autophagy." (PMID 34917515, 2021). "In line with this, higher biglycan levels could be linked to a high intra-tumoral inflammatory reaction that may result in an increased tumor response, and thereby a better prognosis." (PMID 34917515, 2021). "Indeed, high levels of BGN were associated with tumor aggressiveness, such as tumor advanced stages, lymph node invasion, and the presence of metastasis." (PMID 33809543, 2021). "Moreover, BGN expression in preoperative serum was significantly associated with BGN expression in TECs and with tumor malignancy." (PMID 33709550, 2021). "Indeed, we further found that high mRNA levels of BGN are associated with the presence of cancer cells in the lymph nodes, presence of metastasis, and tumor recurrence." (PMID 33809543, 2021). "Interestingly, while biglycan overexpression is associated with higher tumour stages and muscle invasiveness, it’s up-regulation was related with tumour cell proliferation inhibition and increased patients’ 10-year survival." (PMID 29207682, 2017). "Interestingly, higher biglycan mRNA expression was associated with higher tumor stages and muscle invasiveness." (PMID 24223213, 2013). "In addition, high BGN expression was significantly associated with tumor invasion depth (p < 0.001), lymphatic vessel invasion (p = 0.001), and increased expression of CAF markers, αSMA (p = 0.003) and FAP (p = 0.022), and macrophage markers, CD68 (p = 0.049) and CD163 (p = 0.007), in ESCC tissues." (PMID 41465449, 2025). "While these observations were made in non-malignant cells, the fact that biglycan mediates M2 macrophage polarization through autophagy induction suggests that biglycan could be involved in tumor-associated macrophage (TAM) activation during tumor progression at late stages." (PMID 34917515, 2021). "However, HM-tumour cells do not express TGF-β (data not shown), thus there may be another factor secreted from HM-tumours which causes upregulation of biglycan in TECs." (PMID 27295191, 2016). "This study revealed the mechanism by which NR2F2 promotes BGN transcription and tumor progression in PTC." (PMID 41328346, 2026). "In contrast, in immunodeficient nude mice, BGN knockdown still significantly reduced tumor growth, albeit to a lesser extent." (PMID 41328346, 2026). "To further investigate the potential association between BGN and the TME, we performed “ESTIMATE” 42 to evaluate the immune score and tumor purity using bulk RNA-seq data from two PTC cohorts: TCGA-THCA and GSE213647." (PMID 41328346, 2026). "Mounting evidence indicates that BGN is aberrantly overexpressed in both tumor and stromal compartments across multiple malignancies, where its elevated levels correlate with enhanced tumor aggressiveness and poor prognosis." (PMID 41328346, 2026). "In immune-competent C57BL/6J mice, macrophage depletion markedly attenuated the tumor-suppressive effects observed upon BGN knockdown, suggesting that BGN's role in shaping the immune microenvironment is critical for its tumor-promoting activity." (PMID 41328346, 2026).
tumor (continued). "In previous work, it was demonstrated that NR2F2 can bind to and activate the BGN promoter and enhancer regions, promoting its expression and facilitating tumor progression and the formation of an immunosuppressive microenvironment." (PMID 41328346, 2026). "We also sought to delineate the relative contribution of BGN's tumor-intrinsic effects versus its immunomodulatory function." (PMID 41328346, 2026). "To validate these findings in clinical specimens, we measured BGN mRNA levels in tumor and matched adjacent normal tissues from 23 PTC patients." (PMID 41328346, 2026). "Across all five analyzed tissue sections, BGN expression was significantly elevated in malignant tumor spots relative to adjacent normal follicular cell spots." (PMID 41328346, 2026). "Various receptors have been identified as binding partners of BGN; among them, TLRs have been most frequently reported in the context of inflammation and the tumor microenvironment." (PMID 41465449, 2025). "Functional rescue experiments confirmed that BGN overexpression reverses the inhibitory effects of GLIS2 knockdown, while the Wnt/β-catenin inhibitor XAV-939 effectively blocks BGN's tumor-promoting effects." (PMID 40936440, 2025). "Our study thus expands the current understanding of tumor–stromal interactions in ESCC and highlights BGN as a key mediator within its tumor microenvironment." (PMID 41465449, 2025). "Collectively, our findings reveal novel aspects of BGN biology within the ESCC tumor microenvironment and highlight its potential utility as both a prognostic biomarker and therapeutic target." (PMID 41465449, 2025). "This supports the concept that BGN contributes to the establishment of an immunosuppressive tumor microenvironment through the modulation of macrophage function." (PMID 41465449, 2025). "Immunohistochemical analysis of 66 ESCC tissues revealed that high stromal BGN expression correlated with greater tumor invasion, lymphatic invasion, and shorter disease-free survival." (PMID 41465449, 2025). "For example, HER-2/neu-mediated oncogenic transformation leads to the silencing of biglycan expression, which promotes tumor cell proliferation and migration." (PMID 41304707, 2025). "In conclusion, our study demonstrates that BGN is significantly upregulated in CAFs within the ESCC tumor microenvironment and promotes the proliferation and migration of ESCC cells through activation of the Erk and NF-κB pathways via TLR4 signaling." (PMID 41465449, 2025). "The two following patterns of BGN immunostaining were detected: (i) Expression was found in the tumor vessels (including microvascular proliferates), and patched collections of tumor cells (n = 41 in the screening set and n = 40 in the validation set)." (PMID 39762990, 2025). "While BGN shows promise as a tumor marker, its precise mechanism of action in cancer dormancy remains to be fully elucidated." (PMID 40977686, 2025). "Further investigations using animal models are needed to evaluate the physiological relevance of BGN in tumor progression and immune modulation." (PMID 41465449, 2025). "Next, we analyzed the expression of AEBP1-correlated gene BGN (R = 0.901, p < 0.001) in single-cell RNA-seq data, and found that BGN was expressed in fibroblasts of normal tissues, and when cancer occurred, it was mainly expressed in tumor cells." (PMID 40296906, 2025). "BGN is predominantly expressed by CAFs in the tumor microenvironment and interacts with Toll-like receptors (TLR2 and TLR4), which associate with TGFβ/Snail and TNFα/NF-κB signaling pathways to regulate EMT." (PMID 40977686, 2025). "This reduction in biglycan, which acts as a tumor suppressor, supports the uncontrolled growth and spread of cancer cells." (PMID 41304707, 2025). "In particular, these highly expressed genes were notably associated with tumor development and metastatic progression, including A2M, AREG, chemokines (iCAFs-S1), BGN, MFAP5, THBS2, and TIMP1 (iCAFs-S2)." (PMID 39323622, 2024).